PDSS2 (decaprenyl diphosphate synthase subunit 2)
Description:
Heterotetrameric enzyme that catalyzes the condensation of farnesyl diphosphate (FPP), which acts as a primer, and isopentenyl diphosphate (IPP) to produce prenyl diphosphates of varying chain lengths and participates in the determination of the side chain of ubiquinone. Supplies nona and decaprenyl diphosphate, the precursors for the side chain of the isoprenoid quinones ubiquinone-9 (Q9) and ubiquinone-10 (Q10) respectively. The enzyme adds isopentenyl diphosphate molecules sequentially to farnesyl diphosphate with trans stereochemistry. May play a role during cerebellar development (By similarity). May regulate mitochondrial respiratory chain function (By similarity).
Synonyms: C6orf210; DLP1; bA59I9.3; COQ1B; COQ10D3; hDLP1
Tractability: PROTAC: ubiquitination databases record sites on it; its protein half-life has been measured.
Gene: Protein-coding gene on chromosome 6 (107,152,556 to 107,459,580, reverse strand). Ensembl gene ENSG00000164494.
Subcellular location: Mitochondrion
Subcellular location (Human Protein Atlas): Cytosol
Pathways (Reactome):
Metabolism: Ubiquinol biosynthesis
Gene Ontology:
Molecular function: all-trans-decaprenyl-diphosphate synthase activity; protein binding; all-trans-nonaprenyl-diphosphate synthase (geranyl-diphosphate specific) activity; prenyltransferase activity
Biological process: isoprenoid biosynthetic process; ubiquinone biosynthetic process; cerebellum development; lipid metabolic process
Cellular component: cytosol; heterotetrameric polyprenyl diphosphate synthase complex; mitochondrion; mitochondrial matrix; polyprenyl diphosphate synthase complex; protein-containing complex
Genetic constraint (gnomAD): Loss-of-function variants: 16 observed, 29.72 expected, observed/expected ratio (o/e) 0.54, 90% interval 0.36 to 0.82. The upper end of that interval is the gene's LOEUF score, 0.82, which puts it in group 3 of 6, group 1 being the genes least tolerant of losing a copy. Missense variants: 357 observed, 418.39 expected, observed/expected ratio (o/e) 0.85, 90% interval 0.78 to 0.93. Synonymous variants: 138 observed, 162.87 expected, observed/expected ratio (o/e) 0.85, 90% interval 0.74 to 0.98.
Gene-disease validity (ClinGen):
ClinGen rates the evidence that PDSS2 causes each of these diseases.
Leigh syndrome (autosomal recessive): Moderate. A progressive neurological disease defined by specific neuropathological features associating brainstem and basal ganglia lesions.
Homologues: Orthologues: chimpanzee PDSS2 (99% identical), macaque PDSS2 (99% identical), pig PDSS2 (92% identical), rabbit PDSS2 (89% identical), mouse Pdss2 (88% identical), guinea pig PDSS2 (86% identical), dog PDSS2 (80% identical), rat Pdss2 (79% identical), zebrafish pdss2 (59% identical), Drosophila melanogaster Pdss2 (39% identical). Paralogues in human: PDSS1 (25% identical), GGPS1 (13% identical).
Diseases named in the same sentence as PDSS2 in open-access papers:
PDSS2 is named in the same sentence as 51 diseases in open-access papers, as found by Europe PMC text mining. Sharing a sentence is not in itself a finding about the gene and the disease. The quoted sentences say what the papers report.
nephrotic syndrome (8 papers, 2008 to 2025). A collection of symptoms that include severe edema, proteinuria, and hypoalbuminemia; it is indicative of renal dysfunction. "A mouse model harboring a PDSS2 mutation leading to interstitial fibrosis, and a clinical phenotype of nephrotic syndrome progressing to kidney failure, demonstrated significant rescue with high-dose of CoQ10 supplementation." (PMID 39656276, 2025). "More recently, two novel mutations in PDSS2 were reported in a 7-month-old infant with nephrotic syndrome, along with encephalomyopathy, hypertrophic cardiomyopathy, deafness, retinitis pigmentosa, and elevated serum lactate level." (PMID 33426503, 2020). "Compound heterozygous PDSS2 mutations were recently identified in a child with severe Leigh syndrome and nephrotic syndrome." (PMID 18437205, 2008). "Nephrotic syndrome has been seen in individuals with mutations in PDSS2, as well as COQ2." (PMID 18437205, 2008).
hepatocellular carcinoma (7 papers, 2019 to 2024). A malignant tumor that arises from hepatocytes. "It has been shown that the downregulation of PDSS2 can induce a shift from aerobic metabolism to anaerobic glycolysis, as well as increased chromosomal instability—a possible pathogenic mechanism for hepatocellular carcinoma." (PMID 33238568, 2020). "In this study, we demonstrate that high expression of PDSS2-Del2 in HCC is associated with the occurrence and development of hepatocellular carcinoma and promotes tumor metastasis." (PMID 39695147, 2024). "Recent studies have shown that downregulation of PDSS2 gene is found in multiple cancers, such as gastric cancer, hepatocellular carcinoma, melanoma, and lung cancer." (PMID 36860919, 2023). "Recent study also shows that reintroducing PDSS2 into hepatocellular carcinoma can improve mitochondrial complex I activity and inhibits tumor progression in nude mice." (PMID 34489398, 2021). "Hypermethylation of the PDSS2 promoter was detected in hepatocellular carcinoma cells and gastric cancer cells with low PDSS2 expression, and the expression of PDSS2 was re-activated after demethylation." (PMID 31783675, 2019). "Mutations in PDSS2 have been associated with additional phenotypes, including Leigh syndrome, steroid resistant nephrotic syndrome (SRNS)—an atypical manifestation for other mitochondrial disorders but quite common for CoQ10 deficiencies; and hepatocellular carcinoma." (PMID 33238568, 2020).
Leigh syndrome (6 papers, 2014 to 2023). "In human, missense mutations in PDSS2 were reported to cause Coenzyme Q10 (CoQ10) deficiency with Leigh syndrome with nephropathy." (PMID 25166907, 2014).
Ataxia (4 papers, 2017 to 2024). Ataxia refers to impaired coordination of voluntary muscle movement. "Pcp2-cre;Pdss2 loxP/− mice with postnatal Pdss2 deletion in cerebellar Purkinje cells and retinal bipolar neurons exhibited a significant loss in Purkinje cells by 6 mo of age and developed ataxia-like symptoms at 9.5 mo." (PMID 38722242, 2024). "It should be also emphasised that rare autosomal recessive disorder, CoQ10 deficiency (mutation in CABC1; COQ2; COQ9; PDSS1; PDSS2 genes), is frequently associated with seizures, cognitive decline, pyramidal track signs, myopathy, and prominent cerebellar ataxia." (PMID 29456787, 2017). "Interestingly, Pdss2 knockout in mice resulted in cerebellar hypoplasia and in the development of cerebellar ataxia." (PMID 36978966, 2023).
gastric cancer (4 papers, 2019 to 2023). A primary or metastatic malignant neoplasm involving the stomach. "PDSS2 expression was significantly decreased in the tissues of gastric cancer and lung cancers compared with the adjacent normal tissues." (PMID 35204836, 2022). "Immunohistochemistry (IHC) results have revealed low PDSS2 protein levels in the tissues of hepatocellular carcinoma, gastric cancer, and melanoma." (PMID 35204836, 2022). "Studies including our previous report demonstrated that PDSS2 is an important tumor suppressor in the development of malignant melanoma and gastric cancer." (PMID 33064899, 2020). "Previous investigations clearly indicated that the expression levels of PDSS2 are remarkably downregulated in several type of malignant tumors compared with their normal counterparts, including non-small cell lung cancer, primary melanoblastoma, gastric cancer, and liver cancer." (PMID 31783675, 2019).
lung carcinoma (4 papers, 2014 to 2023). "Quantitative RT-PCR analysis further confirmed the downregulation of PDSS2 and its association with the clinical stage in lung cancer tissues." (PMID 36860919, 2023). "Higher SP1 expression and lower PDSS2 expression have been found to be significantly associated with poor prognosis in lung cancer patients." (PMID 35313857, 2022). "Taken together, our results strongly suggest the essential role of Sp1 in maintaining the basic constitutive expression of PDSS2, and the pathogenic implication of Sp1-mediated PDSS2 transcriptional repression in lung cancer cells." (PMID 31783675, 2019). "Of note, the expression of Sp1 and PDSS2 are negatively correlated, and higher Sp1 expression with low PDSS2 expression is significantly associated with poor prognosis in lung cancer." (PMID 31783675, 2019). "This suggested that the tumor-suppressing effects caused by PDSS2 in lung cancer cells might be independent on CoQ10 biosynthesis." (PMID 36860919, 2023). "Sp1-mediated PDSS2 transactivation is implicated in the pathogenesis of lung cancer." (PMID 31783675, 2019). "Both CCK-8 assay and live cell monitoring results showed that knockdown of PDSS2 promoted lung cancer cell growth." (PMID 36860919, 2023). "Bioinformatic analysis of the TCGA dataset revealed that PDSS2 expression was significantly downregulated in lung cancer tissues relative to normal lung tissues." (PMID 36860919, 2023). "Taken together, these results suggested that PDSS2 has significant tumor-suppressing activity in lung cancer cells." (PMID 36860919, 2023). "The expression of this novel transcriptional regulatory axis of SKA2 and PDSS2 also has prognostic value for lung cancer patients, highly suggesting its substantial contribution to human lung cancer progression." (PMID 36860919, 2023). "In this paper, suppressed lung cancer cell malignant phenotype by exogenous overexpression of PDSS2 was observed." (PMID 36860919, 2023). "This novel transcriptional regulatory axis of SKA2 and PDSS2 functionally contributes to human lung cancer progression and is of potential prognostic and therapeutic significances for lung cancer patients." (PMID 36860919, 2023). "Taken together, these findings elucidated that SKA2 promotes lung cancer cell progression at least partially via repressing PDSS2 expression." (PMID 36860919, 2023). "The levels of PDSS2 expression were significantly decreased in lung cancer samples, and lung cancer patients with high expression of SKA2 and low expression of PDSS2 displayed remarkable poor prognosis." (PMID 36860919, 2023). "In the present study, our results showed that all the three PDSS2 mutants showed comparable inhibitory effects on the growth and motility capabilities in lung cancer cells." (PMID 36860919, 2023). "Taken together, these findings strongly suggested that SKA2 accelerates lung cancer cell development through repression of PDSS2." (PMID 36860919, 2023). "The results showed that overexpression of SKA2 alone increased lung cancer cell growth and migration, and these effects were completely abrogated by overexpression of PDSS2." (PMID 36860919, 2023). "The results showed that forced overexpression PDSS2 resulted in significant decrease in lung cancer cell growth." (PMID 36860919, 2023). "Functional analysis revealed that the Sp1 transcription factor is a critical regulator for the constitutive expression, as well as its repressed expression, of PDSS2 in lung cancer cells." (PMID 31783675, 2019). "Overexpression of Sp1 significantly inhibited PDSS2 promoter activity, as well as its endogenous expression, at both mRNA and protein levels in lung cancer cells." (PMID 31783675, 2019). "The results show that the expression of Sp1 is negatively correlated to that of PDSS2 in lung cancer tissues." (PMID 31783675, 2019).
lung carcinoma (continued). "Consistent with analyses of malignant melanoma and lung cancer, most patients with GC harbored a decreased level of PDSS2 mRNA in GC tissues, and the mean PDSS2 expression level was significantly decreased in GC compared with normal adjacent tissues." (PMID 25330808, 2014). "As supplement of CoQ10 was unable to affect the malignant features in lung cancer cells, we speculate that PDSS2 might inhibit the lung cancer cell growth and motility independent of its catalytic activity of CoQ10 biosynthesis." (PMID 36860919, 2023). "Functional analysis revealed that PDSS2 remarkably suppressed lung cancer cell growth and motility." (PMID 36860919, 2023). "In addition, SKA2-mediated lung cancer cell aberrant proliferation and migration can be abrogated by exogenous overexpression PDSS2." (PMID 36860919, 2023). "In addition, Cell motility assay demonstrated that overexpression of PDSS2 also remarkably inhibited lung cancer cell motility." (PMID 36860919, 2023). "We determined whether SKA2-induced lung cancer cell proliferation and migration depends on its repression of PDSS2 expression." (PMID 36860919, 2023). "Our previous study also found that Sp1 could directly mediate the transcription of PDSS2 in lung cancer cells." (PMID 36860919, 2023). "Of note, PDSS2 and SKA2 were associated with clinical outcome in that the worst overall survival was observed in lung cancer patients with high expression of SKA2 and low expression of PDSS2 while the best outcome shown in patients with overexpressed PDSS2 and low expression of SKA2." (PMID 36860919, 2023). "Cell motility assay showed that knockdown of PDSS2 increased lung cancer cell migration capability." (PMID 36860919, 2023). "PDSS2 also has a decreased expression and tumor-suppressing activity in human lung cancer cells." (PMID 31783675, 2019). "Furthermore, we analyzed the expression of PDSS2 and its clinical significance in lung cancer." (PMID 36860919, 2023). "The three PDSS2 mutants were transiently transfected into lung cancer cells, and the results clearly showed that all the three PDSS2 mutants showed obvious inhibitory effects on the growth and motility capabilities of lung cancer cells comparable to the wildtype PDSS2 construct." (PMID 36860919, 2023). "We next investigated whether PDSS2 plays tumor-suppressing role in lung cancer cells." (PMID 36860919, 2023). "Therefore, PDSS2 might serve as a potential novel target gene for diagnose and/or treatment lung cancer patients." (PMID 36860919, 2023). "Finally, we asked whether Sp1-mediated PDSS2 repression exists and represents clinical significance in lung cancer." (PMID 31783675, 2019). "Collectively, our results demonstrated that PDSS2 is a novel downstream target gene of SKA2 in lung cancer cells, and the SKA2-PDSS2 transcriptional regulatory axis functionally contributes to human lung cancer cell malignant phenotypes and prognosis." (PMID 36860919, 2023). "Moreover, PDSS2 may suppress the development of malignant melanomas and lung cancers." (PMID 25330808, 2014). "PDSS2 remarkably suppresses lung cancer cell growth and motility whereas CoQ10 has no obvious effects on lung cancer cell growth and motility, suggesting a non-enzymatic tumor-suppressing activity of PDSS2 in lung cancer cells." (PMID 36860919, 2023). "Taken together, these findings strongly suggest that PDSS2 suppressed lung cancer cell malignant features independent of its catalytic activity of CoQ10 biosynthesis." (PMID 36860919, 2023). "As PDSS2 is the rate-limiting enzyme for CoQ10 biosynthesis and the levels of CoQ10B was also suppressed by overexpression SKA2, we then decided to examine the effect of exogenous CoQ10 treatment on lung cancer cell phonotypes." (PMID 36860919, 2023). "PDSS2 displayed tumor-suppressing activity and could abrogate the SKA2-induced cell proliferation and motility in lung cancer cells." (PMID 36860919, 2023).
lung carcinoma (continued). "In conclusion, this study clearly demonstrated that PDSS2, the first key enzyme for CoQ10 biosynthesis, is a novel downstream transcriptional target of SKA2 in lung cancer cells, and SKA2 represses PDSS2 transcription through the Sp1-binding sites in PDSS2 core promoter." (PMID 36860919, 2023). "And the PDSS2 expression was decreased in lung cancer tissues than in normal samples." (PMID 36860919, 2023). "Furthermore, Kaplan–Meier survival analysis revealed that patients of lung cancer with lower expression of Sp1 and higher expression of PDSS2 exhibited the best disease-free survival, rather than higher expression of Sp1 and lower expression of PDSS2." (PMID 31783675, 2019).
Nephropathy (4 papers, 2014 to 2021). A nonspecific term referring to disease or damage of the kidneys. "Mutations in PDSS2 and COQ2 are also mostly associated with progressive encephalopathy, seizures, and hypertrophic cardiomyopathy, while ADCK4 disease typically manifests as an isolated nephropathy." (PMID 30232548, 2018).
renal failure (4 papers, 2016 to 2025). "The partial loss-of-function mutation of Pdss2 was identified as a spontaneous mutation in a colony of inbred mice and was designated kd because renal failure is the most prominent disease manifestation in mutant kd/kd homozygotes." (PMID 38722242, 2024). "The first reported mutation in Pdss2 appeared spontaneously in an inbred strain of mice and was designated the “kidney disease” (kd) allele because the most prominent phenotype of homozygous mutant mice is kidney dysfunction leading to renal failure." (PMID 38722242, 2024).
glomerular disease (2 papers, 2020 to 2022). "We suggest treating the individuals with biallelic pathogenic variants in COQ2, COQ6, and PDSS2 or presenting phenotype suggestive of CoQ10-related glomerulopathy with oral CoQ10 as early as possible." (PMID 32467597, 2020). "Mutations in genes related to coenzyme Q10, another mitochondrially associated antioxidant, including PDSS1, PDSS2, COQ2, COQ6, and COQ8B/ADCK4, are associated with the development of glomerular disease." (PMID 34874915, 2022).
anemia (1 paper, 2013). A reduction in the number of red blood cells, the amount of hemoglobin, and/or the volume of packed red blood cells. "The patients were comprehensively investigated for common etiologies of anemia, uric acid metabolism and mitochondrial metabolism, including sequencing of several genes (HNF1, UMOD, CoQ2, PDSS2 and partially the mtDNA) but no underlying cause was identified." (PMID 24034276, 2013).
astrocytomas (1 paper, 2022). "It was possible that the tendency of upregulated COQ4 level in Grade III astrocytomas was also a response to downregulated CoQ10 levels and that effect was diminished when PDSS2 level was increased or other abnormalities appeared." (PMID 35204836, 2022). "The high PDSS2 levels in Grade IV astrocytomas might explain why CoQ10 levels in Grade IV astrocytomas slightly rebounded from the decline in Grade III astrocytomas." (PMID 35204836, 2022). "We further investigated whether the decreased CoQ10 levels in astrocytomas was related to the alterations of PDSS2 and COQ proteins." (PMID 35204836, 2022). "Moreover, the positive correlation between PDSS2-b or PDSS2-c levels and the malignancy and the strong upregulation of PDSS2-b indicate an unusual signature of this protein in astrocytomas." (PMID 35204836, 2022). "The alterations were associated with the possible development of mitochondrial abnormalities during progression to a higher astrocytoma grade, which was in line with our hypothesis, although the mechanism for PDSS2 upregulation in astrocytomas remains to be investigated." (PMID 35204836, 2022). "Therefore, the roles of endogenous CoQ10, PDSS2 proteins, and COQ proteins in astrocytomas or human cancers are worth further investigation." (PMID 35204836, 2022). "Therefore, we investigated levels of endogenous CoQ10 versus exogenous α-tocopherol (vitamin E) and of PDSS2 and several COQ proteins in the same control and astrocytoma tissues as used in the previous study." (PMID 35204836, 2022). "The levels of COQ3, COQ5, COQ6, COQ7, COQ8A, and COQ9, but not of COQ4, were lower in Grade IV astrocytoma tissues than in controls or low-grade (Grades I and II) astrocytomas, but PDSS2 levels were higher in astrocytoma tissues than in controls." (PMID 35204836, 2022). "We found significantly higher PDSS2-b level in low-grade, Grade III, and Grade IV astrocytomas than in nontumor controls, and those in Grade IV astrocytomas were also higher than those in low-grade tumors." (PMID 35204836, 2022).